CRP (C-reactive protein)
Diseases named in the same sentence as CRP in open-access papers (continued):
Sharing a sentence is not in itself a finding about the gene and the disease.
cardiovascular disease (continued). "It has been demonstrated that the persistence of increased levels of C-reactive protein and high disease activity are predictors of cardiovascular disease in patients with axial spondyloarthritis." (PMID 38397972, 2024). "An increased level of serum CRP is now considered a marker and predictor of the severity of cardiovascular disease and events." (PMID 38248862, 2024). "In general, the authors emphasize that chronic acute phase protein elevations, such as C-reactive protein (CRP) and serum amyloid A (SAA), increase the risk of cardiovascular disease (CVD) and that even small elevations are relevant." (PMID 38197914, 2024). "For patients with cardiovascular disease, CRP levels positively correlated with AST (r = 0.44, p = 0.006), ALT (r = 0.334, p = 0.043), LDH (r = 0.428; p = 0.011), IL6 (r = 0.704, p = 0.003) and fibrinogen (r = 0.602, p < 0.0001)." (PMID 38474287, 2024). "CRP is often used as a clinical marker of inflammation and increased serum concentrations are consistent predictors of cardiovascular disease, including HF syndrome, in various populations." (PMID 38903584, 2024). "Patients with higher serum urea concentrations at baseline were older (p = 0.01) and more likely to have poor cognitive performance (p < 0.001), depressive symptoms (p = 0.002), cardiovascular disease (p < 0.001), and higher CRP concentrations (p < 0.001)." (PMID 39057966, 2024). "Serum-level of C-reactive-protein was significantly higher (p = 0.002) and history of cardiovascular disease was significantly more frequent (p = 0.023) in patients in which ischemic bowel segments were resected." (PMID 38528270, 2024). "Social isolation (SI) is considered to be a stressor that can lead to many health issues, such as cardiovascular diseases, mental health problems, or even raised blood C-reactive protein (CRP) levels." (PMID 39199534, 2024). "This score predicts various aspects of cardiovascular disease risk by integrating the age and gender of the patient, their systolic blood pressure, total plasma cholesterol levels, HDL, and CRP." (PMID 39625407, 2024). "CRP is a major inflammatory marker, and research has shown that CRP significantly correlates with cardiovascular disease." (PMID 38791032, 2024). "Both low plasma albumin and increased CRP are strong indicators of cardiovascular disease and increased mortality in patients on dialysis." (PMID 39402451, 2024). "Ridker states in his study that the incidence of cardiovascular diseases increased considerably in patients with the highest quartile of C-reactive protein (CRP), a marker of inflammation, compared to those with a lower quartile." (PMID 39519493, 2024). "It was also found that serum CRP concentration and carotid plaque structure closely correlate with the severity of cardiovascular disease." (PMID 38248862, 2024). "A growing body of research suggests that CRP is a biomarker of intravascular inflammation and a key indicator of cardiovascular disease." (PMID 39036884, 2024). "The present study extends these findings by finding that CRP stratified the association of CHIP with HFpEF in the WHI, further implicating inflammation in the association of CHIP with cardiovascular diseases beyond CAD." (PMID 38270950, 2024). "C-reactive protein (CRP) is a biomarker of inflammation and is commonly elevated in cardiovascular diseases." (PMID 39006738, 2024). "High-sensitivity C-reactive protein (hs-CRP) is a sensitive measure of low-grade inflammation and appears superior to conventional blood tests in assessing cardiovascular disease." (PMID 38596631, 2024). "Serum concentration of CRP correlated significantly with the severity of disease, presence of cardiovascular disease (p = 0.006), need of oxygen therapy (p < 0.0001) and computer-scan severity (p = 0.033)." (PMID 38474287, 2024).
cardiovascular disease (continued). "The Health-conscious group was associated with lower levels of inflammatory biomarkers (e.g., C-reactive Protein) which are also known to be elevated in those with common metabolic diseases (e.g., cardiovascular disease)." (PMID 39354608, 2024). "In our study, for patients with cardiovascular disease, CRP levels positively correlated with AST, ALT, LDH, IL6 and fibrinogen." (PMID 38474287, 2024). "In our study group, serum CRP levels correlated significantly with the severity of disease, presence of cardiovascular diseases, need of oxygen therapy and computer scan severity." (PMID 38474287, 2024). "A meta-analysis reported that compared to the control group, patients with cardiovascular diseases have significantly lower testosterone levels, and are more likely to exhibit atherosclerotic plaques and higher levels of C-reactive protein (CRP)." (PMID 39325934, 2024). "For example, MR studies of CRP contributed to its de-prioritisation as a therapeutic target for cardiovascular disease." (PMID 38951047, 2024). "An increasing amount of evidence indicates that C-reactive protein is a reliable indicator of the inflammatory process within blood vessels and a crucial factor in the progression of cardiovascular disease." (PMID 38397957, 2024). "Statins are also effective in downregulating systemic inflammation, as shown by their potential to reduce CRP levels in patients with established cardiovascular disease." (PMID 39335474, 2024). "Commonly used biomarkers, such as high-sensitivity troponin, C-reactive protein, troponin I or troponin T, creatine kinase, B-type natriuretic peptide, and myoglobin, are essential for monitoring and treating cardiovascular diseases." (PMID 39328401, 2024). "C‐reactive protein (CRP) is a widely used inflammatory biomarker, and elevated CRP is related to the higher incidence of cardiovascular diseases." (PMID 38895772, 2024). "Review of the data suggested that a subset of participants presented with levels of CRP and oxi-LDL which would place them at higher risk for cardiovascular disease based on published literature values." (PMID 39215289, 2024). "Keyword analysis further highlighted the pivotal roles of NF-κB, oxidative stress, and CRP in NLRP3 inflammasome-related cardiovascular diseases." (PMID 39022620, 2024). "Studies have shown that Peptostreptococcus was positively correlated with the cardiometabolic biomarker high-sensitivity C-reactive protein, which was involved in the cardiovascular diseases." (PMID 38112416, 2024). "Intriguingly, most of the spectrum of autologous ligands recognized by CRP overlaps with that of antiphospholipid autoantibodies that are related to premature cardiovascular disease in autoimmune syndromes." (PMID 37873776, 2023). "High-sensitivity C-reactive protein (hs-CRP) is an inflammatory marker that has been suggested as a predictor of cardiovascular diseases." (PMID 37215204, 2023). "Observational studies discern that chlorogenic acid precipitates a notable decrement in C-reactive protein (CRP) and IL-6 concentrations in subjects, augments cardiometabolic indices, and exhibits a commendable therapeutic efficacy in cardiovascular disorders." (PMID 37781708, 2023). "CRP protein levels are currently being used as a stable marker in humans for the prediction, prevention and prognosis of cardiovascular disease as well as several other chronic diseases." (PMID 37781386, 2023). "As mentioned, the use of PCT as an individual marker for the assessment of cardiovascular diseases is limited; therefore, the determination of another classical marker of inflammation, for example, CRP, is often performed as well." (PMID 36835296, 2023). "Acute phase response (APR) is characterized by a change in concentration of different proteins, including C-reactive protein and serum amyloid A (SAA) that can be linked to both exposure to metal oxide nanomaterials and risk of cardiovascular diseases." (PMID 36650530, 2023).
cardiovascular disease (continued). "In patients with certain cardiovascular diseases, CRP expression levels was positively correlated with M1 macrophage activation." (PMID 37753091, 2023). "The authors established the potential role of CRP in cardiovascular disease since CRP can bind to LDL cholesterol and is present in atherosclerotic plaques." (PMID 37513660, 2023). "In patients with known cardiovascular disease (CVD), elevated CRP is associated with an increased risk for future CVD events and mortality." (PMID 38293298, 2023). "CRP is a widely used biomarker of inflammation, and it is considered an indicator of the likelihood of cardiovascular disease." (PMID 37108035, 2023). "CXR consolidation; concomitant cardiovascular disease and COPD; and elevated body temperature, AST, serum potassium, and CRP levels, were independent risk factors for rapid deterioration of CXR findings." (PMID 38086863, 2023). "Advantageous effects of APR include tissue repair and recognition of pathogens; however, the two most upregulated acute phase proteins, C-reactive protein (CRP) and serum amyloid A (SAA) are considered risk factors for cardiovascular disease (CVD)." (PMID 36650530, 2023). "Chronically elevated levels of pro-inflammatory markers such as C-Reactive Protein (CRP) and IL-6 are associated with cardiovascular disease, disability, frailty, and mortality." (PMID 37343002, 2023). "A substantial influence on cardiovascular disease pathogenesis seems to be exerted by the more biologically active subunit of CRP, that is, monomeric CRP (mCRP)." (PMID 37158450, 2023). "Fcγ receptors (FcγR) are plasma membrane-associated receptors for IgG and the pentraxins C-reactive protein (CRP), a known risk factor for cardiovascular diseases, and its role on inflammation in cardiovascular disorders have been already investigated." (PMID 37388821, 2023). "CRP, as one of the important inflammatory acute phase proteins, is involved in the development of many cardiovascular diseases." (PMID 37753091, 2023). "First-wave survivors were younger, had lower BMI, fewer cardiovascular diseases, higher CRP max and were more often treated with invasive ventilation, but less frequently with corticosteroids." (PMID 37460259, 2023). "Inflammatory markers, such as C-reactive protein (CRP) and interleukin-6 (IL-6), are associated with an increased risk of cardiovascular disease (CVD) events." (PMID 37908957, 2023). "In this study, we evaluated the effects of genetic variants associated with serum C-reactive protein (CRP) and the risk of five cardiovascular diseases (CVD) using comprehensive two-sample bidirectional Mendelian randomization (MR) analysis." (PMID 37298077, 2023). "This is exemplified by the use of C-reactive protein (CRP) as a biomarker of cardiovascular disease (CVD)." (PMID 37498390, 2023). "Elevated C-reactive protein (CRP) levels are an indicator of inflammation, a major risk factor for cardiovascular disease (CVD)." (PMID 37298077, 2023). "Considering hospitalization for cardiovascular disease, only the presence of syncope and higher CRP values remained inversely predictive." (PMID 35807089, 2022). "C-reactive protein (CRP), a widely used marker of inflammation, is broadly established as a predictor of numerous cardiovascular diseases, including different types of PH." (PMID 35054082, 2022). "These clinical variables include oxygen saturation on room air (P < 0.001), white blood cell count (P = 0.007), lymphocyte count (P < 0.001), c-reactive protein (P < 0.001), and cardiovascular disease (P = 0.020)." (PMID 35031687, 2022). "Haptoglobin, alpha-1-antitrypsin and orosomucoid are reflected in the glycA signal, which has been shown to be an independent and more sensitive marker of inflammation and cardiovascular disease compared to CRP." (PMID 35413834, 2022).
cardiovascular disease (continued). "A positive effect of the anti-aging forest healing program can be expected through the tendency to decrease CRP, a plasma biomarker that is significantly related to chronic stress and cardiovascular disease." (PMID 35457728, 2022). "It is well-established that CRP concentrations in the body is intimately correlated with heart-related diseases, cardiovascular diseases, rheumatoid arthritis, cancer, and inflammation." (PMID 36551147, 2022). "Studies have reported that activated inflammation, which was reflected by the CRP level over 2 mg/L, would predict a high probability of recurrent cardiovascular diseases." (PMID 36278219, 2022). "Various inflammatory indexes, such as blood platelet count, CRP, neutrophil to lymphocyte ratio, and so on, have been investigated in patients with cardiovascular disease and demonstrated to be short or long term prognostic factors." (PMID 36199038, 2022). "Compared with those without myopenia, patients with myopenia in both early and established RA groups had higher levels of ESR and CRP, more active RA, a higher prevalence of cardiovascular diseases, and a lower level of serum albumin." (PMID 36505248, 2022). "Recently, SII is considered to be more specific than CRP or erythrocyte sedimentation rate (ESR) to predict mortality in patients with cardiovascular diseases." (PMID 36030214, 2022). "In contrast, recent large clinical trials suggest that the IL-1β/IL-6/CRP pathway is intimately involved in cardiovascular disease." (PMID 35407379, 2022). "Patients who died were older, had higher incidence of cardiovascular disease and had higher CRP levels than those that survived." (PMID 35684154, 2022). "miR-34a influences lipid metabolism by inhibiting the Sirtuin 1 (SIRT1) pathway as well as stimulating pro-inflammatory cytokines such as IL-1b, IL-7A CRP and TNF-α which are strongly associated with cardiovascular diseases." (PMID 36071532, 2022). "Serum C-reactive protein (CRP) and interleukin-6 (IL-6) are known inflammation biomarkers and independent predictors of cardiovascular disease (CVD) and mortality risk in dialysis patients." (PMID 35458220, 2022). "The acute-phase protein CRP, which is increased in infectious and some cardiovascular diseases, is a biomarker of inflammation." (PMID 36466340, 2022). "There are also studies suggesting the prognostic importance of CRP in various cardiovascular diseases and outcomes after cardiovascular interventions such as percutaneous coronary intervention and coronary artery bypass grafting." (PMID 35244369, 2022). "Lower CRP persisted in Japanese patients with cardiovascular disease (p < 0.06) in the uncomplicated and complicated phases." (PMID 36289811, 2022). "In contrast, German and Japanese patients with cardiovascular disease showed a similar inflammatory response, except for CRP." (PMID 36289811, 2022). "C-reactive protein (CRP) elevation is broadly established as a predictor of numerous cardiovascular diseases and different types of PAH." (PMID 36553040, 2022). "Studies also showed that CRP contributed to abnormal endothelial function, resulting in MetS and cardiovascular disease outcomes." (PMID 35807747, 2022). "CRP has a role in the humoral innate immune response but also contributes to the progression of cardiovascular disease by recognizing and binding to multiple intrinsic ligands." (PMID 36361733, 2022). "Studies in patients with cardiovascular disease have shown that physical activity modulates multiple cytokines, in particular CRP, which is a by-product of the liver metabolism and plays an key role in the acute phase response." (PMID 33796948, 2021). "Whereas, baseline CRP values are recognized as a determinant of the incidence of cardiovascular disease, serum CRP concentration after AMI correlates with the clinical outcome." (PMID 33679775, 2021).
cardiovascular disease (continued). "Several studies have demonstrated that CAR, a new parameter of inflammation introduced in recent years, is superior to CRP and albumin levels alone in determining the inflammatory condition in cardiovascular diseases." (PMID 34406031, 2021). "HRs were adjusted for age, sex, body mass index, cardiovascular disease, dialysis modality, primary kidney disease, use of antithrombotic medication, systolic blood pressure, albumin, C-reactive protein and residual GFR." (PMID 34134634, 2021). "Direct predictors of the composite endpoint were age, CCI, prevalence of cardiovascular disease, and levels of plasma CRP, whereas the only inverse predictor was the estimated glomerular filtration rate." (PMID 34684054, 2021). "C-reactive protein, an independent predictor of cardiovascular disease and an important serum marker of inflammation, was significantly increased in the OS group, indicating an accelerated inflammatory process in this cohort." (PMID 34764876, 2021). "C-reactive protein (CRP) is a marker of chronic inflammation and is associated with the prognosis of various cardiovascular diseases." (PMID 34575381, 2021). "In multivariable analysis, cardiovascular mortality was predicted by D-Dmax > 4.26 mg/l, age > 65 years, prior cardiovascular disease, and C-reactive protein > 3 mg/l." (PMID 33602240, 2021). "Further, high-sensitivity C-reactive protein (CRP) served as a reflection of residual inflammatory risk which has been reported to be associated with both CKD and cardiovascular disease." (PMID 35155621, 2021). "Higher levels of physical activity have been shown to, among other benefits, reduce LDL cholesterol, blood pressure and C-reactive protein levels, all of which are significant intermediators in the development of cardiovascular diseases." (PMID 34702239, 2021). "We measured their blood pressure, endothelial function (by EndoPAT), and risk markers for cardiovascular disease [low-density lioprotein (LDL), homocysteine, C-reactive protein]." (PMID 32725248, 2021). "C-reactive protein (CRP), a strong risk factor for metabolic and cardiovascular diseases, is a commonly used biomarker of meta-inflammation." (PMID 33923291, 2021). "The main studies on NADEs have been related to cardiovascular diseases, where increases in C-reactive protein (CRP) and D-dimer biomarkers have been found in PLWH compared to healthy controls." (PMID 34874239, 2021). "As an indicator of cardiovascular health, suPAR outperforms traditional markers of inflammation such as high sensitivity C-reactive protein (hs-CRP) in prognosticating a range of cardiovascular diseases." (PMID 35155590, 2021). "Although there is paucity in literature discussing the role of CRP in HFpEF, CRP has long known to be correlated with a higher incidence of cardiac events in patients with existing cardiovascular disease (CVD)." (PMID 32030562, 2021). "The top five prognostic predictors were lactate dehydrogenase (≥250 U/L, HR:23.11), C-reactive protein (>10mg/l, HR: 12.34), D-dimer (≥0.5 mg/L, HR: 11.29), urea (>7.5 mmol/L, HR: 9.93), and cardiovascular disease (HR: 8.87), respectively." (PMID 33561834, 2021). "Inflammatory biomarkers, such as CRP, are used as surrogates for IL-1 activity and have been shown to predict adverse outcomes in patients across a wide spectrum of cardiovascular disease." (PMID 34749739, 2021). "The advent of high-sensitivity CRP measurement in the 1990s, alongside experimental and clinical evidence suggesting a potential role of inflammation in cardiovascular disease a few years later, increased research interest in CRP." (PMID 32978716, 2021). "C-reactive protein (CRP) is a biomarker associated with inflammatory processes, cardiovascular diseases." (PMID 33925825, 2021). "Among the cardiovascular disease patients, the level of CRP and IL-6 was generally decreased after 12 weeks of the n-3 supplement." (PMID 34822400, 2021).